VIM (vimentin)
Diseases named in the same sentence as VIM in open-access papers (continued):
Sharing a sentence is not in itself a finding about the gene and the disease.
sarcoidosis (continued). "Recent data show that in patients with an acute, self-resolving form of sarcoidosis, Löfgren's syndrome, there are increased quantities of anti-vimentin antibodies in the BAL fluid." (PMID 32256501, 2020). "Strong T cell responses to vimentin, a peptide derived from the cytoskeleton, have been found in a subset of patients with sarcoidosis with a specific HLA type." (PMID 32722050, 2020). "In summary, our results demonstrate sarcoidosis to be associated with an antigen- and HLA-DRB1*03-restricted humoral immune response to vimentin." (PMID 30038611, 2018). "Together, these data suggest a self-contained in situ adaptive immune response to the vimentin C-terminus in sarcoidosis patients, which is particularly pronounced in those expressing HLA-DRB1*03." (PMID 30038611, 2018). "Together, these studies reveal the presence of linked in situ recognition of vimentin by both T- and B-cells in HLA-DRB1*03+ sarcoidosis patients, associated with a selective humoral immune response to the vimentin C-terminus." (PMID 30038611, 2018). "As demonstrated here in sarcoidosis, and previously in lupus nephritis, vimentin expression is strongly upregulated at sites of inflammation." (PMID 30038611, 2018). "Perhaps more importantly, measurement of cytokine secretion in response to one of our identified proteins, vimentin, is shown here to be significantly greater from sarcoidosis PBMCS than those from patients with tuberculosis." (PMID 28114394, 2017). "Using two complementary proteomic approaches we identified 74 proteins specific to sarcoidosis tissue and found that one, vimentin, induced the similar pattern of cytokine secretion from sarcoidosis PBMCs." (PMID 28114394, 2017). "Previous work supports the involvement of several of our identified cytoskeletal proteins in sarcoidosis e.g. tubulin and vimentin have been detected in Schaumann bodies and vimentin was also found within asteroid bodies of sarcoidosis granulomas." (PMID 28114394, 2017). "Stimulation with both Kveim reagent and vimentin induces a specific pro-inflammatory cytokine secretion from sarcoidosis PBMCs." (PMID 28114394, 2017). "A comparative analysis of our two independently generated 1D- and 2D-proteomic datasets identified 3 proteins (vimentin, tubulin and α-actinin-4) that were found in sarcoidosis tissue only and were identified through both 1D-SDS-PAGE and 2D-DIGE." (PMID 28114394, 2017). "One group identified a number of vimentin peptides by mass spectrometric sequencing after affinity-purification of HLA-DR molecules (HLA-DRB1*0301) from bronchoalveolar lavage (BAL) cells of sarcoidosis patients." (PMID 28114394, 2017). "Vimentin-peptides were amongst the identified peptides, suggesting antigenic properties of vimentin in the sarcoidosis lung." (PMID 28114394, 2017). "Immunohistochemical staining of our spleen tissue showed increased abundance of vimentin in sarcoidosis spleens localized particularly to tissue granulomas when compared to healthy spleen." (PMID 28114394, 2017). "Increased cytokine secretion was subsequently observed with vimentin stimulation of sarcoidosis PBMCs vs. tuberculosis PBMCs (IFN-γ: 396.6 pg/mL vs 0.1 pg/mL, p = 0.0009; TNF-α: 1139 pg/mL vs 0.1 pg/mL, p<0.0001)." (PMID 28114394, 2017). "Vimentin, a structural protein encoded by the VIM gene, may be involved in the pathogenesis of sarcoidosis." (PMID 40002701, 2025). "Sera from 93 patients with sarcoidosis, 55 patients with non-infectious lung diseases and 40 healthy subjects was examined for presence of autoantibodies to mutated citrullinated vimentin (anti-MCV)." (PMID 36010289, 2022). "Using an regression algorithm, we identified a panel of 11 IgM autoantiboides including BPI, Fibrinogen IV, Hemocyanin, Histone H2B, Histone H3, Matrigel, Prothrombin protein, Sm, SmD, TPO and Vimentin, which can efficiently distinguish between sarcoidosis and healthy controls." (PMID 36264970, 2022).
sarcoidosis (continued). "Among them, only vimentin stimulation induced an IFN-γ/TNF-α-based inflammatory response from sarcoidosis PBMCs; interestingly, IFN-γ and TNF-α were significantly higher in sarcoidosis-derived PBMCs than in tuberculosis-derived and healthy control-derived PBMCs." (PMID 36148452, 2022). "The presence of antibodies in patients with tuberculosis and sarcoidosis may reflect the relationship between the pathogenesis of those diseases with the possibility of cross-reactivity between vimentin and M. tuberculosis peptides." (PMID 36010289, 2022). "Vimentin is a self-antigen that has been found in the lungs of sarcoidosis patients, although more validation is required to determine whether immune responses to vimentin are involved in disease initiation and progression." (PMID 32256501, 2020). "IHC staining identified increased vimentin especially localized to granulomas in sarcoidosis patient spleens and stimulation of sarcoid peripheral blood mononuclear cells with vimentin induced higher IFN-γ and TNF-α secretion compared to those of tuberculosis patients or healthy controls." (PMID 33036432, 2020). "Importantly, our data suggest that lung-secreted AVAs in sarcoidosis reflect both an amplification of normal homeostatic immunity and a shift in antigenic specificity from the vimentin N-terminus to the C-terminus." (PMID 30038611, 2018). "We stimulated our PBMCs with whole vimentin protein but individual epitopes of the protein might have differing levels of stimulating capacity in sarcoidosis." (PMID 28114394, 2017). "An alternative hypothesis is that vimentin, together with other proteins, may serve as a self-antigen capable of eliciting cytokine responses from sarcoidosis PBMCs, potentially in a CD4+ T-cell mediated fashion." (PMID 28114394, 2017). "If validated in larger cohorts, the cellular responses to vimentin may assist with clinical differentiation between diseases such as sarcoidosis and tuberculosis." (PMID 28114394, 2017). "Clearly, M. tuberculosis is not the only trigger of sarcoidosis, and many different antigens have been suggested — by epidemiological associations (e.g., pine pollens), animal studies (Propionibacterium acnes), and in vitro and human studies (vimentin)." (PMID 38165044, 2024). "However, the proposal of vimentin as an autoantigen in sarcoidosis suggests autoimmune involvement." (PMID 36010289, 2022). "For the sarcoidosis Kv-reaction, one potential hypothesis is that vimentin merely upregulates cytokine responses from sarcoidosis PBMCs as it is known that other proteins such as mycobacterial-derived antigenic peptides and serum amyloid A can cause a similar response in sarcoidosis." (PMID 28114394, 2017). "Based on our previous work and those of others we also chose a stimulation time similar to that used with stimulation of tuberculosis PBMCs but again, it may be that sarcoidosis PBMCs responding to Kv and vimentin need a different incubation time and this should be investigated further." (PMID 28114394, 2017). "A more recent study has also hypothesised this same role for vimentin in sarcoidosis." (PMID 28114394, 2017). "These two observations alone suggest a coordinated epitope shift to the vimentin C-terminus for both B- and T-cell in situ adaptive immunity especially in HLA-DRB1*03+ sarcoidosis patients." (PMID 30038611, 2018). "In sarcoidosis patients, we identified both an increased AVA response in situ and a shift in vimentin epitopes targeted by AVAs to the C-terminal domain." (PMID 30038611, 2018). "Bronchoalveolar lavage fluid (BALF) and serum from 48 sarcoidosis patients and 15 healthy volunteers were typed for HLA-DRB1*03 and titrated for antibodies to full-length vimentin, vimentin truncations, and total IgG and IgA by ELISA." (PMID 30038611, 2018).
sarcoidosis (continued). "The autoimmune nature of sarcoidosis needs further evaluation, thereby the purpose of this study was to determine the presence of autoantibodies to various vimentin modifications in patients with sarcoidosis and other non-specific lung diseases." (PMID 36010289, 2022). "The results of this study suggest that citrullination, as well as vimentin modification, are not the main triggers in the initialization of an autoimmune reaction in patients with sarcoidosis." (PMID 36010289, 2022). "Several autoantibodies, including anti-mitochondrial, anti-nuclear, anti-double stranded DNA, anti-citrullinated cyclic peptide, rheumatoid factor, anti-vimentin, and anti-negative elongation factor E, have been detected in sarcoidosis." (PMID 33881596, 2021). "Vimentin has been eluted from HLA-DR molecules expressed on BAL cells from some patients with sarcoidosis, and vimentin-specific autoantibodies are found in BAL fluid of sarcoidosis patients." (PMID 32256501, 2020). "After stimulation with vimentin, the median IFN-γ concentration was significantly elevated in the supernatant of sarcoidosis (396.6 pg/mL IQR 0.1–657.1) vs. tuberculosis (0.1 pg/mL IQR 0.1–0.1, p = 0.0009) and healthy volunteer PBMCs (0.1 pg/mL IGR 0.1–0.1, p = 0.014)." (PMID 28114394, 2017). "Various antigens have been incriminated as potential stimuli in sarcoidosis, such as viral and bacterial infections, including pathogens like mycobacteria and Propionobacterium acnes, organic and non-organic substances, as well as self-antigens like vimentin." (PMID 40520830, 2025). "The low concentration of the anti-CCP antibodies and the positive correlation of anti-MCV and anti-Sa antibodies suggest that citrullination and modification of vimentin is not a key factor in the development of an autoimmune response in patients with sarcoidosis." (PMID 36010289, 2022). "Similarly, stimulation of peripheral blood mononuclear cells (PBMCs) from patients with sarcoidosis with vimentin triggers increased secretion of cytokines able to sustain the immune response, suggesting a self-perpetuating mechanism similar to that known to occur in autoimmune diseases." (PMID 32722050, 2020). "We could not demonstrate a vimentin-specific response in all sarcoidosis patients." (PMID 28114394, 2017). "Non-infectious mechanisms proposed in sarcoidosis pathogenesis include autoimmune responses to self-antigens or DAMPs, such as serum amyloid A (SAA), vimentin, and various environmental exposures." (PMID 41197661, 2025). "In the present study we investigated the levels and frequency of autoantibodies to different modifications of vimentin (MCV, Sa and non-modified vimentin) and CCP in serum from patients with sarcoidosis and other lung disorders." (PMID 36010289, 2022). "A total of 17.6% of these cats, including two of the three cats with feline sarcoid and the cat with the tumor negative for BPV4 and negative for all antibodies except vimentin, were alive at the time of the study, reflecting a time frame from 2.3 to 7.5 years (832 to 2732 days)." (PMID 38612342, 2024).
COVID-19 (22 papers, 2020 to 2025). A disease caused by infection with severe acute respiratory syndrome coronavirus 2. "Based on the evidence of vimentin's direct interaction with the SARS-CoV spike protein throughout the spike-ACE2 attachment process, we postulated that high expression of vimentin might be a susceptibility factor of testis tissue in the severely affected cases who died of COVID-19." (PMID 39866583, 2024). "Considering some limitations, vimentin can be used as a biomarker option for testicular damage following COVID-19-induced orchitis." (PMID 39866583, 2024). "The present study showed that vimentin expression was significantly high in the testis tissues of cases who died of severe COVID-19." (PMID 39866583, 2024). "Taken together, the existing evidence suggests a link between vimentin expression and COVID-19-induced orchitis." (PMID 39866583, 2024). "Similar to data from immunostaining, the gene expression level of vimentin was significantly upregulated in the COVID-19 group in comparison to the control group (p < 0.05)." (PMID 39866583, 2024). "Immunostaining data demonstrated an increased expression of vimentin (as a potential co-receptor for SARS-CoV-2) in the COVID-19 group in comparison to controls (p < 0.001)." (PMID 39866583, 2024). "The possible role of vimentin targeting compounds in treating COVID-19 has been suggested by in vitro and in vivo models of SARS-CoV-2 infection with an investigational small molecule (ALDR491)." (PMID 35683351, 2022). "Here, we report the potent preclinical efficacy of ALD-R491, a vimentin-targeting small molecule compound, in treating COVID-19 through its host-directed antiviral and anti-inflammatory actions." (PMID 34634931, 2021). "VIM (Vimentin), involved in cytoskeletal dynamics, may support Tregs’ mobility and infiltration into inflamed COVID-19 tissues, aiding targeted suppression of inflammation." (PMID 39975141, 2025). "Based on these data, vimentin overexpression in the testis tissue of COVID-19 cases, as observed in the present study, may also play a role during the uncontrolled immune response, a characteristic of SARS-CoV-2 infection." (PMID 39866583, 2024). "Recently, vimentin was shown to mediate the entry of the SARS-CoV-2 virus into the cells; therefore, its high levels in the COVID-19 group may indicate placentas’ susceptibility to SARS-CoV-2 infection." (PMID 39057113, 2024). "We have also identified spike-binding proteins in saliva, most notably vimentin, which correlates with increased viral infectivity in vitro and could serve as a therapeutic target for COVID-19." (PMID 38007005, 2024). "Vimentin could facilitate SARS-CoV-2 infection and contribute to vascular complications associated with COVID-19." (PMID 35078919, 2022). "Our study is the first to show the role of a vimentin-targeted drug in the management of COVID-19." (PMID 35683351, 2022). "However, in all the COVID-19 cases analyzed (n=13), vimentin expression and positive cells significantly increased (quantification)." (PMID 34671353, 2021). "There may be a strong link between vimentin expression and COVID-19-induced orchitis." (PMID 39866583, 2024). "Then, using an innovative technique known as spike-baited mass spectrometry, we identified novel spike-binding proteins in saliva, most notably vimentin, which correlated with increased viral infectivity in vitro and could serve as a therapeutic target against COVID-19." (PMID 38007005, 2024). "Additionally, the absence of vimentin in knockout mice results in insensitivity to inflammation and acute lung injury (associated with COVID-19)." (PMID 34372621, 2021). "Moreover, drugs that are effective in fighting COVID-19 also reduce vimentin expression." (PMID 34372621, 2021). "The levels of COVID-19 microenvironment markers, i.e., CD3, CD4, CD8, CD20, CD68, vimentin, NP, ACE2, Granzyme B, E-cadherin, and phosphorylated nuclear factor kappa B (p-NFκB), were measured via IMC." (PMID 39100091, 2024).
COVID-19 (continued). "A significant expression of vimentin and infiltration of immune cells (CD68+, CD38+, and CD138+) in the testicular tissue of COVID-19 cases, along with extensive immunoglobulin G precipitation and reduced inhibin expression (p = 0.001) were observed." (PMID 39866583, 2024). "CD34 expression was lower in the COVID-19 group (p = 0.048), while CD4, CD68, and vimentin levels were higher in the COVID group (p < 0.05)." (PMID 39057113, 2024). "For example, we identify CYTOR, a lncRNA associated with granulocyte survival strongly upregulated in COVID-19 patient group G1, which was accompanied by strong induction of CYTOR interactors such as VIM and PIK3CB." (PMID 33441124, 2021). "Sera from 10 patients with AIS during COVID-19, 10 non-COVID-19 stroke patients, 20 COVID-19 and 30 healthy donors (HD) were analyzed for anti-cardiolipin, anti-β2-GPI, anti-phosphatidylserine/prothrombin and anti-vimentin/CL antibodies by ELISA." (PMID 36936925, 2023). "No clinical studies on the role of vimentin-targeting agents on COVID-19 have been reported to date." (PMID 35683351, 2022). "Interestingly, expression of CYTOR was significantly increased in severe COVID-19 patient group G1 (p < 0.001) and correlated with both PIK3CB (r = 0.53, p < 0.001) and VIM (r = 0.55, p < 0.001)." (PMID 33441124, 2021). "Vimentin immunostaining used to visualize endothelial cells and reactive astrocytes highlighted perivascular astrocytes only in old COVID-19 patients, while parenchymal astrocytes in both old and young COVID-19 patients were vimentin-negative." (PMID 35785352, 2022).